BRD7 (bromodomain containing 7)
Diseases named in the same sentence as BRD7 in open-access papers (continued):
Sharing a sentence is not in itself a finding about the gene and the disease.
tumor (57 papers, 2008 to 2026). "We further identified BRD7 as Hpa2-interacting protein and found that attenuation of tumor growth is associated with the nuclear positioning of Hpa2 and BRD7." (PMID 39695102, 2024). "Taken together, these results indicate that BRD7 deficiency sensitizes tumor cells to CHK1 inhibitors, and CHK1 accumulation by BRD7 deficiency plays a causal role in promoting chemosensitization." (PMID 37626049, 2023). "Biologically, the increased expression of CHK1 in tumor cells caused by BRD7 silencing significantly increased cell sensitivity to CHK1 inhibitors by enhancing tumor cell apoptosis, and this effect was reversed by the simultaneous knockdown of CHK1 or USP1." (PMID 37626049, 2023). "Next, we examined the biological consequences of CHK1 up-regulation induced by BRD7 deficiency in tumor cells." (PMID 37626049, 2023). "BRD7 expression is also reported to be associated with the clinical characteristics in HCC (tumor size, tumor stage, and survival)." (PMID 30521023, 2018). "Together with the results of the correlation analysis, which revealed a significant association between decreased BRD7 expression and tumor size, these findings indicated that BRD7 plays key roles in preventing the growth of tumor cells during HCC development." (PMID 26919247, 2016). "A significant increase in CHK1 levels and activity in tumor cells caused by the silencing of BRD7 enhances tumor cell sensitivity to CHK1 inhibitors, leading to increased cell death via apoptosis, which is reversed by the simultaneous knockdown of CHK1 or USP1." (PMID 37626049, 2023). "However, given the multiple signaling pathways involved in the tumor suppressive effect of BRD7, the target genes and functional networks associated with BRD7 have not yet been clearly explored in the context of HCC." (PMID 33531996, 2021). "Notably, in three of the seven patients that carried the NMD mutations in CHD1L, DPF2 and BRD7, the genes were down-regulated in these tumor tissues while the same genes in the other patients showed significant up-regulation (FDR < 0.05)." (PMID 31429776, 2019). "The same NMD mutation in the BRD7 gene was also found in a patient from TCGA and BRD7 gene expression in that tumor was also found to be decreased by 5.74 fold, highlighting that nonsense mutations may play an important role in regulating gene expression." (PMID 31429776, 2019). "Furthermore, we investigated the molecular mechanism underlying the function of the BRD7/miR-141 axis in cell proliferation and tumor growth of NPC." (PMID 27010857, 2016). "BRD7 protein expression was strongly associated with clinical stage and tumor size." (PMID 26919247, 2016). "To determine the potential anti‐tumour effects of BRD7‐targeted demethylation in NPC, we conducted in vitro experiments using NPC cells stably expressing dCas9‐TET1CD‐sgRNA2&5." (PMID 41510594, 2026). "To further validate the impact of the demethylation system on the expression and methylation levels of BRD7 in vivo, we ground a portion of the tumour tissue for RNA and protein extraction." (PMID 41510594, 2026). "Overall, these in vivo data suggest that targeted demethylation of BRD7 is a potential anti‐tumour strategy." (PMID 41510594, 2026). "Tumor tissues from mice were collected to elucidate the molecular mechanisms by which BRD7 inhibited NPC growth and immune escape in vivo." (PMID 40083706, 2025). "We further investigated the effect of the TRIM25/BRD7 axis on tumor growth and PTX resistance in vivo." (PMID 41315221, 2025).
tumor (continued). "The results showed that compared with the siNC group, TRIM25 knockdown slowed tumor growth and reduced tumor weight, whereas the recovery expression of BRD7 reversed the inhibitory effect of TRIM25 knockdown." (PMID 41315221, 2025). "We found that overexpression of BRD7 in tumor cells inhibited the apoptosis of CD8+ T lymphocytes in the co-culture system, reduced the proportion of PD-1+ T cells, and increased IFN-γ secretion." (PMID 40083706, 2025). "Along with its PBAF partners, BRD7 participates in β cell regulation or the resistance of tumor cells to immune cells." (PMID 38954484, 2024). "We conclude that Hpa2 induces the expression and nuclear localization of a strong tumor suppressor such as BRD7, while BRD7 can interact with Hpa2 and shuttle it to the cell nucleus." (PMID 39695102, 2024). "Under BRD7 deficiency and CHK1 accumulation, the CHK1 inhibitors induced higher tumor cell apoptosis, with improved efficiency in killing tumor cells and reduced side effects." (PMID 37626049, 2023). "In our study, we found that BRD7 negatively regulated CHK1 levels in a variety of tumor cells and shortened CHK1 half-life by binding to and promoting CHK1 ubiquitination." (PMID 37626049, 2023). "An increasing number of studies have found that BRD7 expression is decreased or lost in human cancers, which is in line with its role as a tumor suppressor." (PMID 36674511, 2023). "Collectively, these in vivo results are consistent with the patterns observed in the in vitro experiments and further confirm that BRD7 inhibits tumor metastasis at least partially by negatively regulating BIRC2 transcriptional activity and expression." (PMID 36788209, 2023). "We reported that BRD7 effectively suppressed cell proliferation and tumor growth in vitro and in vivo." (PMID 35371302, 2022). "The anti-tumor effects of TP-422 were associated with changes in the expression of extracellular matrix and apoptotic genes, suggesting that either BRD7 or BRD9 or both promote tumor growth and invasiveness." (PMID 35323214, 2022). "In this study, we demonstrated the ability of BRD7 to suppress cell proliferation and tumor growth in vitro and in vivo." (PMID 35371302, 2022). "Our previous study demonstrated that BRD7 expression is significantly associated with a favorable prognosis in HCC patients and is involved in impeding tumor development by inhibiting proliferation, cell cycle progression, and cellular migration/invasion." (PMID 33531996, 2021). "Subsequently, we confirmed the tumor-promoting properties of BRD7, including cell proliferation, cell cycle progression, and tumor growth, in vitro and in vivo." (PMID 34109174, 2021). "To further confirm the functional roles of the BRD7/c-Myc axis in tumor growth and progression, we established a xenograft model in nude mice with BRD7 knockdown and BRD7 knockdown with simultaneous c-Myc restoration in HCT116 and SW620 cells." (PMID 34109174, 2021). "These divergent findings suggest that the mechanism by which BRD7 exerts its antitumor effect is complex and variable and that it is highly reliant on the specific tumor type." (PMID 33531996, 2021). "BRD7 functions as a tumor suppressor, and low expression of BRD7 serves as an independent factor for prognosis and is positively associated with the clinical stage of cancer progression." (PMID 34109174, 2021). "The in vivo assays also revealed that BRD7 promotes cell proliferation and tumor growth through facilitating the G1/S phase transition of the cell cycle." (PMID 34109174, 2021).
tumor (continued). "Taken together, our findings demonstrated that targeting c-Myc attenuates the effect of BRD7 on tumor growth and cell cycle progression in vivo." (PMID 34109174, 2021). "Further, consistent with multiple studies demonstrating a critical role for BRD7 in the progression of multiple cancers 11,30, our previous study confirmed that BRD7 acts as an anti-tumor factor in HCC progression." (PMID 33531996, 2021). "Recent evidence has demonstrated that BRD7 also serves as a tumor suppressor by regulating tumor-related signaling pathways involved in cell growth, mobility and cell cycling 28,29." (PMID 33531996, 2021). "It is suggested that BRD7 has a significant “functional duality” in different stages of the occurrence and development of CRC, and it is different from the role of tumor inhibition in other tumors, which is also a novel finding for BRD7 functions." (PMID 34109174, 2021). "BRD7 also induces ferroptosis in hepatic stellate cells, which raises the possibility that BRD7 also plays a role as a tumor suppressor by regulating cell death through iron-dependent accumulation of lipid hydroperoxides." (PMID 32992509, 2020). "How BRD7 differentially regulates β-catenin in different cell types and how this effect is related to its role as a tumor-suppressor remain to be resolved." (PMID 32992509, 2020). "Higher mRNA and protein expressions of BRD7 were found in HCC, and mRNA expression of BRD7 was correlated with cancer stages and tumor grades." (PMID 32927435, 2020). "One XB type tumour (YOPC31) had mutations in the DNA damage pathway (RAD50, RAD51, BLM and BRD7), with the highest mutational burden (6.24 mutations/Mb), but the TIDE score of this tumour indicated lower responsiveness to anti-PD-1/PD-L1 therapy." (PMID 32235905, 2020). "BRD7 was initially recognized as a tumor suppressor, but recent studies have provided evidence that BRD7 participates in the regulation of metabolism and insulin signaling pathway with detailed mechanistic underpinnings." (PMID 32992509, 2020). "BRD7, a member of the bromodomain-containing protein family, was identified as a critical tumor suppressor in multiple types of cancers, including NPC and breast cancer and also involved in many physiological processes." (PMID 29559001, 2018). "Similar to ARID2, BRD7 is also a component of the SWI/SNF remodeling machinery and a putative tumor suppressor reported with significant truncating mutations in HCC." (PMID 30521023, 2018). "And more and more evidences showed that BRD7 were downregulated in some tumor cells including epithelial ovarian carcinoma, breast cancer and colorectal carcinoma." (PMID 29212240, 2017). "Bromodomain‐containing protein 7 (BRD7) is a tumour suppressor that is known to regulate many pathological processes including cell growth, apoptosis and cell cycle." (PMID 27957794, 2017). "We confirmed suppressed BRD7 expression both in isolated EC and reduction of BRD7 expression in tumor endothelium was independently observed in different xenografted tumors on the CAM, suggesting a generic cancer feature." (PMID 28951988, 2017).
tumor (continued). "A notable exception was bromodomain containing 7 (BRD7) that triggered our interest by its previously proposed tumor suppressor function in different types of cancer." (PMID 28951988, 2017). "BRD7 inhibits mitogenic signaling, tumorigenesis and angiogenesis and stimulates anti-tumor immunity through different possible pathways." (PMID 28951988, 2017). "Accumulating evidence showed that BRD7 is involved in multiple cancers and serves as a tumor suppressor, including HCC." (PMID 29212240, 2017). "BRD7 has been described as a putative tumor suppressor protein, which prompted us to further investigate its role in tumor angiogenesis." (PMID 28951988, 2017). "The reported downregulation of BRD7 in cancer prompted us to further elucidate the role of BRD7 in tumor angiogenesis." (PMID 28951988, 2017). "With INF-γ treatment, we confirmed that BRD7 regulates the tumor suppression activity of XAF1 in vivo." (PMID 26802028, 2016). "In parallel experiments, a role for BRD7 in inhibiting tumor growth was also observed in injectable mouse models." (PMID 26919247, 2016). "BRD7 expression was also detected in adjacent non-tumor tissues, which exhibited stronger BRD7 immunoreactivity compared with tumor tissues." (PMID 26919247, 2016). "Consistent with the differences in BRD7 mRNA levels, decreased BRD7 protein expression was observed in HCC tumor tissues compared with non-tumor tissues (P = 0.001)." (PMID 26919247, 2016). "We also evaluated the functional role of BRD7 in HCC tumor progression by examining colony formation, proliferation, cell cycle, migration and invasion in vitro." (PMID 26919247, 2016). "The mouse model experiments further showed that BRD7 overexpression significantly inhibited tumor growth." (PMID 26919247, 2016). "Immunohistochemical analyses of the 159 paraffin-embedded HCC surgical specimens suggested that BRD7 expression is predominantly localized to the cytoplasm in tumor cells." (PMID 26919247, 2016). "In the present report, we demonstrated for the first time that APC/Ccdh1 and APC/Ccdc20 regulate BRD7 protein stability and its anti-tumor function." (PMID 24840027, 2014). "BRD7, a member of the bromodomain protein family, has been shown to act as a tumor suppressor by binding the acetylated histones in chromosomes." (PMID 24840027, 2014). "SPLUNC1, UBAP1, BRD7, NAG7, NOR1, NGX6 and LTF genes were found to be tumor suppressor/susceptibility genes in different stages of NPC." (PMID 19949542, 2009). "Aberrant promoter methylation of BRD7 gene was detected in 18 of 18 (100%) tumor biopsies and 18 of 18 (100%) matched blood samples of NPC patients, respectively." (PMID 18778484, 2008). "In the present study, among the 18 NPC patients, aberrant promoter methylation of BRD7 gene was detected in 100% of tumor biopsies and matched blood samples of NPC patients." (PMID 18778484, 2008). "Nested methylation-specific PCR and RT-PCR were employed to detect the methylation status of BRD7 promoter and the mRNA expression of BRD7 gene in tumor cell lines as well as clinical samples." (PMID 18778484, 2008). "Importantly, we demonstrated that the lentiviral particles encapsulating this system can effectively activate BRD7 expression and exert anti‐tumour effects." (PMID 41510594, 2026). "This suggests that this demethylation system may inhibit tumour progression by transcriptionally activating BRD7 and thus regulating these pathways." (PMID 41510594, 2026). "Therefore, we next utilised lentivirus with stable expression of LentiCRISPRv2/dCas9‐TET1CD‐sgRNA2&5 targeting demethylated BRD7 to evaluate the anti‐tumour effect in xenograft tumour." (PMID 41510594, 2026). "Therefore, targeting BRD7 demethylation can serve as an important molecular strategy for activating BRD7 and subsequent tumour treatment." (PMID 41510594, 2026).
tumor (continued). "Although we have demonstrated that BRD7 demethylation system can effectively activate the expression of BRD7 and thereby exerts significant tumour suppressive effects, the success of future clinical applications will largely depend on the efficiency of delivery and safety." (PMID 41510594, 2026). "The demethylation system constructed based on CRISPR/dCas9 and lentiviral delivery technology, LentiCRISPRv2/dCas9‐TET1CD‐sgRNA (sgRNA1‐5), can activate BRD7 expression to varying degrees and inhibit the proliferation of tumour cells, with sgRNA2 and sgRNA5 showing the most significant effects." (PMID 41510594, 2026). "Overexpression of BRD7 can suppress tumor growth in vivo, and the inhibitory effect on tumor growth is more pronounced when BRD7 was overexpressed simultaneously with T cell injection, further enhanced by the use of Atezolizumab, which significantly inhibited tumor growth in vivo." (PMID 40083706, 2025). "If BRD7 could downregulate the PD-1 levels of T cells, the mechanism of T cells internally regulates their killing function against tumor cells still needs further exploration." (PMID 40083706, 2025). "Taken together, these findings suggest that BRD7 may promote tumor cell death by inhibiting the repair of radiotherapy-induced DSBs, which may be a potential mechanism through which BRD7 enhances the radiosensitivity of NPC cells." (PMID 39664566, 2024). "BRD7, alone or in complex with Hpa2, binds to acetylated histone 3 and affects gene transcription related to various biological processes, ranging from embryonic development to tumor progression." (PMID 39695102, 2024). "The paralog, BRD7, has context-dependent tumor suppressive or tumor-promoting functions." (PMID 38390898, 2024). "In this study, BIRC2 was identified as a direct target of BRD7, which functions as a transcriptional regulatory factor to inhibit carcinogenesis and tumor progression at least partially by negatively regulating the enhancer activation and expression of BIRC2 in NPC." (PMID 36788209, 2023). "Therefore, the exact mechanism of BRD7 functions as a tumor-suppressor by influencing its target genes has rarely been reported." (PMID 36788209, 2023). "Our data shows that the increased expression and activity of CHK1 induced by BRD7 silencing could be a promising strategy to enhance the chemosensitivity of tumor cells to CHK1 inhibitors." (PMID 37626049, 2023). "Since the bromodomain of BRD7 is critical for its tumor suppressor activity 10, 11, we then tested whether the bromodomain of BRD7 was required for the inhibition of MDM2 phosphorylation." (PMID 35371302, 2022). "We found that BRD7 knockdown significantly inhibited tumor growth in both HCT116 and SW620 cells." (PMID 34109174, 2021). "In addition, the tumor weight was markedly reduced in the BRD7 knockdown group compared with the control group, while restoring c-Myc expression reversed BRD7 knockdown-mediated tumor growth inhibition in both HCT116 and SW620 cells." (PMID 34109174, 2021).